DANCR (differentiation antagonizing non-protein coding RNA)
Diseases named in the same sentence as DANCR in open-access papers (continued):
Sharing a sentence is not in itself a finding about the gene and the disease.
glioma (continued). "To investigate the role of DANCR in glioma progression, we suppressed DANCR expression in glioma cells by transfected siRNAs, and the knockdown efficiency was confirmed by qRT-PCR (P<0.05)." (PMID 29301870, 2018). "Inhibition of DANCR suppressed the glioma cells proliferation and induced cells arrested in the G0/G1 phase." (PMID 29301870, 2018). "Results showed that miR-634 was significantly decreased in glioma tissues and inversely correlated with DANCR expression in glioma tissues (P<0.05)." (PMID 29301870, 2018). "In glioma cells, DANCR functions as a competitive endogenous RNA for miRNAs such as miR-33a-5p, miR-33b-5p, miR-1-3p, miR-206 and miR-613 to drive the malignant progression of glioma." (PMID 38877534, 2024). "Numerous studies have indicated that DANCR may serve as an oncogenic factor crucial for glioma onset, progression, and other malignant traits." (PMID 38877534, 2024). "In glioma, DANCR knockdown leads to decreased proliferation and migration." (PMID 36497269, 2022). "DANCR expression was significantly higher in glioma cells than in normal human astrocytes." (PMID 34722539, 2021). "DANCR via activating AXL/PI3K/Akt/NF-κB signaling pathway could mediate cisplatin resistance in glioma cells." (PMID 34178658, 2021). "Similarly, DANCR promotes glioma progression by acting as a sponge of miR-634, thus modulating RAB1A, which has an important role in tumor progression." (PMID 33980320, 2021). "Furthermore, intriguingly, DANCR expression is negatively correlated with cisplatin sensitivity in glioma cells." (PMID 33638615, 2021). "Thus, knockdown of DANCR inhibits migration, invasion, and proliferation of glioma cells via sponging of miR-135a-5p." (PMID 33980320, 2021). "Forced FOXO1 suppresses the cell growth through G2/M cell cycle arrest and increases apoptosis in glioma, whereas silencing of DANCR could repress the ubiquitination of FOXO1 in osteoblast differentiation and reduce the amount of DANCR bound to FOXO1." (PMID 35141227, 2021). "Knockdown of DANCR inhibited cell proliferation, migration and invasion in glioma cells." (PMID 32099526, 2020). "Furthermore, we found that DANCR acted as a ceRNA to regulate BMI1-mediated effects on progression of glioma via sponging miR-135a-5p." (PMID 32099526, 2020). "Through upregulating AXL, DANCR activated PI3K/Akt/NF-κB signaling pathway in glioma cells." (PMID 33123287, 2020). "In this study, we explored the expression level of DANCR in glioma tissues and cells." (PMID 32099526, 2020). "DANCR could directly interact with miR-634 in glioma cells and this interaction results in the inhibition of downstream of RAB1A expression." (PMID 33123287, 2020). "Some literatures have revealed several target miRNAs of DANCR in glioma." (PMID 32099526, 2020). "In conclusion, DANCR was upregulated in glioma tissues and cells." (PMID 32099526, 2020). "Moreover, the correlation between DANCR expression and prognosis of glioma patients was measured, and patients with high DANCR expression (n = 19) had poor survival compared with low DANCR expression (n = 14)." (PMID 32099526, 2020). "Here, we first identified miR-135a-5p as a target of DANCR in glioma cells." (PMID 32099526, 2020). "In addition, it has been proved that high expression of DANCR predicts poor prognosis for glioma patients." (PMID 32099526, 2020). "Knockdown DANCR inhibited cell proliferation, migration and invasion in glioma cells." (PMID 32099526, 2020). "For instance, DANCR regulated RAB1A expression in glioma by functioning as a ceRNA of miR-634." (PMID 32099526, 2020). "DANCR was upregulated and miR-135a-5p was downregulated in glioma tissues and cells." (PMID 32099526, 2020). "Moreover, we displayed that BMI1 and DANCR were negatively correlated with miR-135a-5p in glioma tissues, and DANCR was positively correlated with BMI1." (PMID 32099526, 2020).
glioma (continued). "For example, lncRNA DANCR may act as a competing endogenous RNA to regulate Ras-related protein RAB1A expression by sponging miR-634 in glioma." (PMID 31216644, 2019). "To explore whether DANCR exerted biological functions through miR-634, we reduced expression miR-634 in si-DANCR transfected glioma cells (P<0.05)." (PMID 29301870, 2018). "To further investigate the role of DANCR on glioma cells cycle, we used flow cytometry." (PMID 29301870, 2018). "To examine whether DANCR has a similar mechanism in glioma, we used bioinformatics software DIANA to predict the potential miRNA binding sites in DANCR." (PMID 29301870, 2018). "We also evaluated the expression of DANCR in glioma cell lines." (PMID 29301870, 2018). "Taken together, these results indicated that DANCR could act as a sponge for miR-634 to up-regulate the expression of RAB1A in glioma." (PMID 29301870, 2018). "The present study demonstrated that DANCR/miR-634/RAB1A axis plays crucial roles in the progression of glioma, and DANCR might potentially serve as a therapeutic target for the treatment of glioma patients." (PMID 29301870, 2018). "Furthermore, knockdown of DANCR revealed its role as the ceRNA that regulates expression of B-lymphoma Moloney murine leukemia virus insertion region-1 (BMI1), a self-renewal gene that is associated with tumorigenesis and progression of cancer in glioma." (PMID 33980320, 2021). "Notably, DANCR may be a good target for the treatment of glioma patients, as its normal activity can contribute to malignancy and poor prognosis of glioma." (PMID 35141227, 2021). "Besides, lncRNA DANCR could mediate cisplatin resistance in glioma cells via activating the AXL/PI3K/Akt/NF-κB signaling pathway." (PMID 30910838, 2021). "In addition, DANCR expression was negatively correlated with cisplatin sensitivity in glioma cells." (PMID 33123287, 2020). "In addition, we explored the relationship between the DANCR and miR-135a-5p in glioma and the results showed that overexpression DANCR conspicuously reduced the level of miR-135a-5p expression, while inhibition of DANCR remarkably elevated the expression of miR-135a-5p in LN229 and U251 cells." (PMID 32099526, 2020). "In addition, DANCR could bind to miR-135a-5p, and its elevated expression reversed miR-135a-5p inhibition-mediated progression of glioma." (PMID 32099526, 2020). "Furthermore, we also analyzed the relationship among miR-135a-5p, DANCR and BMI1, and found that expression levels of BMI1 and DANCR were negatively correlated with miR-135a-5p abundance in glioma tissues, and expression of DANCR was positively correlated with BMI1 level." (PMID 32099526, 2020). "In addition, miR-135a-5p was a direct target of DANCR, and its elevated expression could reverse miR-135a-5p inhibition-mediated progression of glioma." (PMID 32099526, 2020). "In addition, DANCR has been reported to promote glioma malignancy by miR-33a-5p." (PMID 32099526, 2020). "Furthermore, we found that miR-634 inhibitor could reverse the effect of DANCR knockdown on glioma cells." (PMID 29301870, 2018). "Thus, in the present study, we hypothesized that lncRNA DANCR contributed to glioma progression by function as a miRNA sponge." (PMID 29301870, 2018). "Moreover, we explored miR-634 expression in DANCR knockdown glioma cells." (PMID 29301870, 2018). "In addition, we verified that DANCR could directly interact with miR-634 in glioma cells and this interaction resulted in the inhibition of downstream of RAB1A expression." (PMID 29301870, 2018). "However, the effect of DANCR in glioma progression and underlying molecular mechanisms were not entirely explored." (PMID 29301870, 2018). "Our results indicated that DANCR could act as an oncogenic lncRNA in glioma progression." (PMID 29301870, 2018). "Pearson correlation coefficient in glioma tissues identified a positive correlation between IGF2BP2 and DANCR expression." (PMID 35141227, 2021).
glioma (continued). "To identify the potential relationship between IGF2BP2 and DANCR in glioma, we conducted a correlation analysis through GEPIA, which indicated a significant correlation between them, whereas DANCR was also identified to be highly expressed in glioma." (PMID 35141227, 2021). "Collectively, IGF2BP2 inhibits PID1 expression through the DANCR/FOXO1 axis, inducing drug resistance in GBM cells, and promoting glioma progression." (PMID 35141227, 2021). "The expression levels of DANCR, miR-135a-5p and BMI1 were measured by qRT-PCR in glioma tissues and cells." (PMID 32099526, 2020). "For instance, the upregulation of DANCR promotes glioma progression via Wnt signaling 18, and SNHG3 promotes glioma development by suppressing the expression of KLF2 and p21 expression." (PMID 32913464, 2020). "Very recently, emerging studies indicated that lncRNA DANCR and GHET1 were sponges of miR-216a in glioma cells in regulating cell progression and angiogenesis." (PMID 33817241, 2020). "Our study discovered a novel mechanism that DANCR served as a molecular sponge for miR-634 and regulated RAB1A in glioma progression." (PMID 29301870, 2018). "In summary, our studies indicated that DANCR promoted glioma progression by functioning as miR-634 sponge, and indicated a novel DANCR-miR-634-RAB1A signaling pathway regulatory network in glioma." (PMID 29301870, 2018). "Similarly to DANCR, SNHG6 was shown to promote glioma progression via a similar ceRNA activity by interfering with glioma-relevant miRNAs: miR-543 and miR-101-3p." (PMID 36497269, 2022). "Collectively, DANCR knockdown inhibited cell proliferation, migration and invasion of glioma through regulating miR-135a-5p/BMI1, providing viable therapeutic avenues for treatment of glioma." (PMID 32099526, 2020). "We found that the level of DANCR expression was drastically higher in glioma tissues than normal tissues." (PMID 32099526, 2020). "Moreover, DANCR acted as a ceRNA to regulate BMI1 expression and BMI1-mediated effects on progression of glioma by sponging miR-135a-5p." (PMID 32099526, 2020). "Furthermore, DANCR acted as a ceRNA to regulate BMI1 expression and BMI1-mediated effects on progression of glioma by sponging miR-135a-5p." (PMID 32099526, 2020). "To determine whether DANCR could function as a ceRNA for RAB1A via modulating miR-634 in glioma, we determined the mRNA and protein levels of RAB1A after glioma cells transfected with si-DANCR combined with miR-634 inhibitor." (PMID 29301870, 2018). "Results showed that DANCR inhibition suppressed RAB1A expression in glioma cells both at mRNA and protein levels, and miR-634 inhibitor restored the reduction of RAB1A expression in DANCR suppressed glioma cells (P<0.05)." (PMID 29301870, 2018). "Additionally, DANCR upregulates AXL, a receptor tyrosine kinase that activates the PI3K/Akt/NF-κB signaling pathway by competitively binding with miR-33a-5p, miRNA-33b-5p, miR-1-3p, miR-206 and miR-613 to mediate the cisplatin resistance in gliomas." (PMID 33980320, 2021). "However, there are no more reports on target miRNAs of DANCR in glioma." (PMID 32099526, 2020). "However, whether DANCR affected glioma progression by regulating miRNAs has not yet been reported." (PMID 29301870, 2018).
breast carcinoma (24 papers, 2017 to 2025). "Recently, abnormal elevation of DANCR has been reported to be associated with a variety of human malignancies, such as breast cancer, ovarian cancer, colon cancer and osteosarcoma." (PMID 35907897, 2022). "In breast cancer samples, over-expression of DANCR has been associated with involvement of lymph nodes as well as hormone receptor and HER2 expressions." (PMID 35590326, 2022). "DANCR is highest expressed in TNBC subtype among breast cancer subtypes and associated with TNBC metastasis." (PMID 33443534, 2021). "Emerging evidence demonstrates that DANCR is a cancer-associated lncRNA abnormally expressed in many cancers (e.g., lung cancer, gastric cancer, breast cancer, hepatocellular carcinoma)." (PMID 34722539, 2021). "Lnc-DANCR is known to be upregulated in advanced breast cancer and is associated with metastasis." (PMID 39830662, 2024). "DANCR and PVT1 are other lncRNAs implicated in promoting breast cancer cell proliferation through specific signaling pathways." (PMID 39912983, 2025). "Several lncRNAs have been identified as positive regulators of breast cancer cell proliferation, including DANCR, PVT1, CCAT1, KCNQ1OT1 and SPRY4-IT1." (PMID 39912983, 2025). "DANCR overexpression significantly enhances breast cancer cell proliferation, migration, and invasion." (PMID 40370195, 2025). "Mechanistically, DANCR sequestering miR-34c-5p in breast cancer cells and enhanced cell proliferation and migration." (PMID 39119602, 2024). "Previous research has shown that Lnc-DANCR knockdown leads to breast cancer cell cycle arrest in the G0/G1 phase." (PMID 39830662, 2024). "DANCR silencing not only has stalled proliferation, migratory potential, and invasiveness of breast cancer cells, but also has induced their apoptosis." (PMID 35590326, 2022). "Another mechanism of involvement of DANCR in the pathogenesis of breast cancer is mediated through enhancement of the EZH2 binding to the promoter of SOCS3, which results in suppression of expression of SOCS3." (PMID 35590326, 2022). "Subsequent studies demonstrated that DANCR is overexpressed in many human malignancies, including lung, liver, colon, gastric and breast cancers." (PMID 33123287, 2020). "High expression of DANCR has been recently found in human cancers and DANCR acts as a tumor promoter in multiple malignancies such as ovarian cancer, gastric cancer, breast cancer and so many like this." (PMID 32423468, 2020). "DANCR was significantly up‐regulated in tissue samples from patients with breast cancer, as well as in breast cancer cell lines, as compared with normal tissues and breast epithelial cells, respectively." (PMID 31860165, 2020). "Lastly, on the molecular level, the activities of DANCR in normal, early‐ or late‐stage breast cancer cells were achieved by EZH2‐mediated epigenetic down‐regulation of SOCS3." (PMID 31860165, 2020). "In breast cancer, DANCR upregulates PI3K/AKT signaling through activating serine phosphorylation of RXRA." (PMID 31804607, 2020). "DANCR was necessary and sufficient to control multiple malignant phenotypes of breast cancer cells in vitro and xenograft growth in vivo." (PMID 31860165, 2020). "qRT‐PCR analysis showed that DANCR was significantly up‐regulated in breast cancer tissues compared with normal tissues (P = 0.009)." (PMID 31860165, 2020). "DANCR expression was markedly upregulated in breast cancer cell lines as compared to that in MCF10A cell lines." (PMID 30518934, 2018). "DANCR showed significantly higher expression level in TNBC than that in the other subtypes of breast cancer." (PMID 30518934, 2018). "Notably, DANCR expression was downregulated in breast cancer tissues compared to that in matched normal adjacent tissues." (PMID 38877534, 2024). "Conversely, DANCR inhibition promotes the EMT in human breast cancer cells." (PMID 38877534, 2024). "Interestingly, DANCR expression was notably diminished in highly metastatic breast cancer cell lines." (PMID 38877534, 2024).
breast carcinoma (continued). "Additionally, E2F1 enhanced DANCR transcription by directly binding to its promoter in breast cancer cells." (PMID 39119602, 2024). "Silencing DANCR could lead to the inhibition of the malignant proliferation of breast cancer cells and the promotion of cell apoptosis and autophagy." (PMID 37125193, 2023). "Among the lncRNAs, NRAD1 and DANCR were significantly associated with higher hazard ratios in basal-like breast cancers but not TNBC patients." (PMID 32244924, 2020). "Boosting SOCS3 expression may reverse the oncogenic activities of DANCR and thus provide a therapeutic strategy for breast cancer treatment." (PMID 31860165, 2020). "Thirdly, in normal breast epithelial cells or breast cancer cells of low malignancy, overexpression of DANCR was sufficient to promote EMT, cancer stemness, and inflammation, indicating its potency in inducing tumorigenesis and malignant transformation during breast cancer oncogenesis." (PMID 31860165, 2020). "DANCR not only essentially maintained these phenotypes in late‐stage TNBC but also sufficiently induced them in normal breast epithelial cells or early‐stage breast cancer cells." (PMID 31860165, 2020). "Our data indicate that DANCR is a pleiotropic oncogenic lncRNA in breast cancer." (PMID 31860165, 2020). "We report for the first time that DANCR essentially contributed to all three malignant phenotypes of breast cancer, which, on the molecular level, was mediated through EZH2‐controlled epigenetic regulation of suppressor of cytokine signaling 3 (SOCS3) via H3K27 trimethylation." (PMID 31860165, 2020). "In addition to knocking down DANCR in malignant breast cancer cells, we also stably increased its level in normal breast epithelial cells, MCF10A, or breast cancer cells of low malignancy, MCF7, using lentivirus‐mediated gene expression." (PMID 31860165, 2020). "Xenograft animal study was performed to validate whether DANCR knockdown could inhibit breast cancer cell growth and migration in vivo." (PMID 30910842, 2019). "Furthermore, some studies showed that DANCR regulate breast cancer through binding and phosphorylating EZH225." (PMID 30518934, 2018). "Thus, DANCR was validated as an oncogene in breast cancer, and targeting DANCR may have therapeutic value in BC." (PMID 34722539, 2021). "To assess whether DANCR regulates EMT or cancer stemness of malignant breast cancer cells, we first examined the expressions of EMT‐related biomarkers, including SNAIL1, SLUG, MMP‐2, MMP‐9, E‐cadherin, and Vimentin in shDANCR vs. shNC (MDA‐MB‐231 and MDA‐MB‐468) cells." (PMID 31860165, 2020). "First, DANCR was up‐regulated in breast tissues (specifically in those associated with advanced pathological grades or positive lymph node metastasis) as well as in highly malignant and metastatic TNBC cells, supporting the clinical relevance of DANCR in breast cancer." (PMID 31860165, 2020). "Therefore, DANCR might act as a tumor promoter by targetting miRNA-216a-5p, which might provide a potential therapy target for breast cancer treatment." (PMID 30910842, 2019). "Nevertheless, a few studies also revealed the opposite function of DANCR as a tumor suppressor in breast cancer, renal cell carcinoma and nonsmall cell lung cancer, which may result from the obvious tissue-specific expression patterns of lncRNAs than protein-coding genes." (PMID 31383847, 2019). "DANCR could be a potential target for the treatment of breast cancer." (PMID 28760736, 2017). "Another study has shown over-expression of DANCR and VAPB in breast cancer cells, parallel with down-regulation of miR-4319." (PMID 35590326, 2022).